TNF (tumor necrosis factor)
Diseases named in the same sentence as TNF in open-access papers (continued):
Sharing a sentence is not in itself a finding about the gene and the disease.
asthma (continued). "The treatment also reversed the OVA-induced increase of IL-4, TNF-α, and decrease in IL-10 and IFN-γ in these mice, indicating its anti-inflammatory role in obese asthma." (PMID 37893170, 2023). "It has been proven that patients with severe asthma express more TNF-α, and a unique TNF-α phenotype has recently been reported in children with moderate-to-severe asthma." (PMID 36982980, 2023). "Among the top 25 keywords of all four time periods, ROS, COPD, asthma, lung injury, cancer, biomarker, smoke, inflammation, apoptosis, caspase, catalase, glutathione, MDA, SOD, and TNF-alpha appeared during at least three periods." (PMID 37305540, 2023). "Finally, the strategic role of TNF-α in asthma pathogenesis is well known: its immunoreactivity is increased in the airways of patients with mild asthma, its expression is increased markedly in patients with severe asthma, and it is shown to induce and exacerbate bronchial hyperresponsiveness." (PMID 37298721, 2023). "We found that the mRNA expression levels of several inflammatory factors, such as IL-4, IL-5 and TNF-α, were significantly lower in the PP121 group than in the asthma group." (PMID 37936054, 2023). "TNF, VEGFA and IL-18 were the other top targets identified to be explored for therapeutic benefit in asthma but need further clinical testing." (PMID 37735578, 2023). "Different to glucocorticoid treatments, GGsTop was able to suppress expressions of IFNγ, TNFα and MCP-1, the three key factors in steroid resistant asthma." (PMID 37377967, 2023). "Both TNF-α and IFN-γ increased chemokine production in ASM cells from subjects with asthma compared to unstimulated ASM cells (the basal)." (PMID 37299150, 2023). "Clinical observations have especially shown that the proinflammatory cytokines mainly produced by macrophages (e.g., TNF-α, IL-1β, IL-6, and MCP-1) are increased in the BALF of patients with asthma." (PMID 37107297, 2023). "ASM is an important target for corticosteroid therapy and IFN-γ and TNF-α have a significant effect on ASM, which is responsible for the insensitivity to corticosteroids in patients with severe asthma." (PMID 37377958, 2023). "TXL is able to suppress inflammation and apoptosis induced by TNF-α through suppressing MMP10, suggesting the potential effect of TXL against asthma." (PMID 35000533, 2022). "Th1 cytokines, TNFα and IFNγ, have substantial pro-inflammatory effects on ASM that contribute to airway inflammation, hyperresponsiveness, and remodeling in asthma, however little is known about their combined effects on ASM gene expression." (PMID 35578269, 2022). "IL-6, TNF, and AKT, which occupied an important position in asthma and IPF, are essential targets regulated by BSYQ decoction." (PMID 35672815, 2022). "Several studies reported that the expression of TNF-α, TGF-b, IL-1B, and α-SMA genes is significantly increased in OVA-induced asthma in animals, which is consistent with our findings." (PMID 35774748, 2022). "To further understand the effects of TNFα and IFNγ on corticosteroid sensitivity in the context of neonatal and pediatric asthma, we performed RNA sequencing (RNA-seq) on human pediatric ASM treated with fluticasone propionate (FP), TNFα, and/or IFNγ." (PMID 35578269, 2022). "Meanwhile, IL-4 and TNF-α values in both COPD and ACO were significantly higher than those in asthma." (PMID 36311545, 2022). "The levels of TNF-α, TNFR2, and CCL-9 in the asthma model group increase, while the levels of IFN-γ, IL-1α, ICAM-1, and IL-4 increased in the Majie cataplasm group, especially IFN-γ and IL-1α." (PMID 35600943, 2022). "Effects of TNFα and IFNγ enhanced several pro-inflammatory genes and pathways related to ASM and its contributions to asthma pathogenesis, which persisted in the presence of corticosteroids." (PMID 35578269, 2022). "IL6, IL-1β, TNF, VEGFA, AKT1, etc., played an essential role in the PPI network, indicating the crucial roles in treating asthma and IPF." (PMID 35672815, 2022).
asthma (continued). "CAD significantly decreased the content of TNF-α, IL-13, IL-4, IL-1β and IL-5 in the bronchoalveolar lavage fluid (BALF), IL-17, IL-6, and OVA-specific IgE in serum and increased serum IFN-γ in asthma mice." (PMID 36213326, 2022). "To evaluate the effects of simultaneous administration of TNF and IL-6 inhibitors, we measured the number of Th17-cells in the lungs of mice with HDM-induced asthma." (PMID 35408882, 2022). "When the expression of CD38 was examined in ASM cells, a molecule involved in AHR and airway inflammation in asthma, GC was unable to inhibit CD38 expression when cells were treated with the combination of TNFα and IFNγ." (PMID 36012240, 2022). "In conclusion, this study demonstrates that, similar to human patients with asthma, horses with sEA have increases in CXCL-8, TNF-α, and IFN-γ compared to clinically healthy horses." (PMID 36713876, 2022). "Amongst these cytokines, the involvement of TNFα and IFNγ in GCI in asthma received significant attention over the past decades." (PMID 36012240, 2022). "After the intervention of Majie cataplasm, the content of TNF-α, TNFR2, and CCL-9 was lower than that in the asthma model group." (PMID 35600943, 2022). "Despite the mRNA expression levels of asthma related immune factor genes (INF-γ, TNF-α) showing a rising trend in the asthmatic model, suggesting that inflammation plays a significant role in asthma development." (PMID 36439114, 2022). "Western blotting analysis results suggest that the expression of TNF-a and TL1A/DR3 remarkably increased in OVA-induced asthma model compared with control group." (PMID 35359966, 2022). "Oral administration of CSE (0.53 or 5.3 mg/kg) to rats reversed IL-4, -5, and TNF-α levels in both body fluids (serum and BAL) of animals in comparison to asthma group." (PMID 38143476, 2022). "Further examination of protein targets that were identified to be suppressed in response to the combined activity of IL-17A/F and TNF-α could provide valuable mechanistic data for delineating molecular processes related to the pathophysiology of neutrophilic airway inflammation and severe asthma." (PMID 36517803, 2022). "For the inflammatory cytokines in the lung, the contents of TNF-α, TNFR2, CXCL-9, CCL-12, CCL-9, CCL-2, and CCL-5 in the asthma model group were higher than those in the control group, while the contents of GM-CSF and IL-1α were decreased." (PMID 35600943, 2022). "A previous study revealed that the level of the Th1-derived cytokines tumor necrosis factor (TNF)-α and interferon (IFN)-γ were increased in some severe asthma patients who were resistant to corticosteroid therapy." (PMID 35252347, 2022). "In this study, cytokine/chemokine concentrations in BALF revealed elevated TNF-α and CXCL-8 in sEA horses; therefore, these are potential targets for further subclassification and treatment in asthma." (PMID 36713876, 2022). "Neutrophilic asthma and airway remodeling are not fully understood, but several studies have shown that inflammatory mediators, such as LTB4, IL-6, IL-8, and TNF-α, which are related to neutrophilic inflammation, were elevated in an asthmatic airway." (PMID 35626330, 2022). "The specific neutralization of TNF-a by infliximab on the TL1A/DR3 axis and EMT was observed in mice with OVA-induced asthma." (PMID 35359966, 2022). "This study first proposed that the TL1A/DR3 axis was significantly upregulated in patients and mice with both asthma and high TNF-a expression and in TNF-a-stimulated epithelial Beas-2B cells." (PMID 35359966, 2022). "Based on clinical studies, the herbal formula significantly reduced TNF-α production by murine macrophages (RAW 264.7 cells) and peripheral blood mononuclear cells (PBMCs) from asthma patients." (PMID 35630531, 2022). "Proinflammatory cytokines such as IL-1β, IL-6 and TNF-α are found in increased amounts in the sputum and BALF of patients with asthma." (PMID 35804727, 2022).
asthma (continued). "To deepen our understanding of possible functional interaction between TNF and IL-6 in the context of allergic asthma, in the present study using a mouse model of HDM-induced asthma we examined the effects of combined IL-6 and TNF inhibition." (PMID 35408882, 2022). "In the present study, we confirmed that TNF inhibition abrogated Th2-mediated eosinophilia in mice with HDM-induced asthma." (PMID 35408882, 2022). "The levels of inflammatory cytokines IL‐4 and TNF‐α were increased while IL‐10 and IFN‐γ were decreased in obese asthma; metformin reversed these changes." (PMID 33421348, 2021). "In ACO mice, there was an overlap of asthma and COPD with marked increases of total leukocytes, neutrophils, and eosinophils counts and higher levels of inflammatory cytokines (IL-4, IL-6, TNF-α, IL-1β, IL-17A, and IFN-γ) in BALF." (PMID 33869177, 2021). "Neutrophils, activated lymphocytes, natural killer cells, endothelial cells, mast cells, and mononuclear phagocytes all produce tumor necrosis factor (TNF)-α, which is involved in the pathogenesis of asthma." (PMID 33503170, 2021). "In contrast, the pathobiology of T2-low asthma typically involves Th1 and Th17 cells, neutrophils and several proinflammatory cytokines such as IL-1β, IL-6, IL-17A, IL-17F, IFN-γ and TNF-α." (PMID 34777398, 2021). "OVA stimulation increased the expressions of IL‐4 and TNF‐α and decreased the expressions of IL‐10 and IFN‐γ in the BALF and plasma, in obese asthma, while metformin reversed these changes." (PMID 33421348, 2021). "Study has found that asthma was more severe in patients with excessive cytokine expression, such as IL6, IL1B, and TNF-α." (PMID 34221070, 2021). "In chronic obstructive pulmonary disease patients, the PVT1 expression positively correlated with the GOLD stage and levels of TNF-α, IL-6, IL-8, and IL-17; PVT1 exacerbates the inflammation and cell-barrier injury during asthma by regulating miR-149." (PMID 33506021, 2021). "The Haemophilus-predominant subgroup had decreased α diversity and enhanced proinflammatory mediators, IL-1β and TNFα, consistent with previous observations in both COPD and asthma." (PMID 33332995, 2021). "In the asthma model, OVA together with TLR ligands (LPS/flagellin) or house dust extract (HDE) as adjuvants induced a similar accumulation of TNF, IL-1a, IL-1b, and GM-CSF in BALF pointing to the possible role of LPS in the effect with HDE." (PMID 35387007, 2021). "The MSC-pANGPT1 (angiopoietin 1 gene) were aerosolized in a rabbit OVA-induced asthma and reduced the expression of pro-inflammatory cytokine genes (IL-4, TNF, TGF-β, and MMP-9), which can be an additional beneficial effect in asthma treatment." (PMID 33959015, 2021). "CS-resistant severe asthmatics typically exhibit a T2-low asthma, wherein several pro-inflammatory cytokines including IFN-γ, TNF-α, IL-6 and IL-12 mediate its pathogenesis." (PMID 34777398, 2021). "Compared to the asthma and COPD groups, higher levels of IL-4, IL-6, TNF-α, IL-1β, IL-17A, and IFN-γ in ACO were observed, and there were significances in IL-4, IL-6, TNF-α, and IFN-γ compared to the control group (P < 0.01)." (PMID 33869177, 2021). "In KEGG pathway enrichment analysis, the differential expression proteins were enriched in chemokine signaling pathway, TNF signaling pathway, and IL-17 signaling pathway, PI3K-Akt signaling pathway, which has been reported closely related to asthma." (PMID 34630102, 2021). "The results show that glucocorticoid treatment in patients with moderate asthma results in HDAC1 increase and restrain TNF-α and HAT and, therefore, suppresses Nf-kB and through that restrains IL-8." (PMID 33781317, 2021). "Th1 and Th17- type responses have also been shown to play a role in asthma pathogenesis, and elevated levels of IFN-γ, TNF-α, and IL-17A can be found in the serum of asthmatic patients." (PMID 32194407, 2020).
asthma (continued). "It turned out that the mRNA expressions of several inflammatory factors, such as tumor necrosis factor (TNF), Muc5ac, IL-4, IL-13, and IL-12b were significantly upregulated in asthma group compared with control and diacerein groups." (PMID 33013396, 2020). "In asthma-COPD overlap, the serum TNF-α concentration in patients with FEV1 > 80% (4.5 [2.5; 10.2] pg/ml) was lower than that in other examined patients with this disease (p < 0.05)." (PMID 32733164, 2020). "In summary, epithelial-derived mediators such as CCL5, IL-1, IL-8, IL-6 and TNF-α drive mesenchymal-mediated inflammation that promotes TH2, eosinophilic and neutrophilic inflammation in different asthma subtypes." (PMID 32679790, 2020). "Higher serum levels of TNF-α, IL-13, IL-4, IL-10, hs-CRP and FeNO were determined in asthma patients than in healthy volunteers (P<0.05)." (PMID 33223504, 2020). "Many of the mediators (e.g., TGF-β1/2, ET-1, TSP-1, CCL5, IL-1, IL-8, IL-6, TNF-α, BNP), highlighted in this review to drive epithelial-mesenchymal cross-talk have previously been identified in asthma pathogenesis." (PMID 32679790, 2020). "The expression level of Th1 mediated cytokines, such as TNFα, and IL-1β were significantly higher in ACO cases with respect to asthma and controls." (PMID 32448302, 2020). "We used our method to quantify GN, GP bacteria, blaTEM gene, IL-6, and TNF-α in human BALF samples from 11 healthy subjects and 23 subjects with asthma." (PMID 32451375, 2020). "For example, there was cross-sectional evidence for blood leukocyte DNA methylation at TNF-alpha mediating the relationship between MEHP and asthma among children from three study populations." (PMID 31275917, 2019). "TNF-α can act directly on smooth muscle and increase the contractile response to several spasmodic agents which can contribute to AHR in asthma." (PMID 31019244, 2019). "The third study assessed the cytokines tumor necrosis factor (TNF) and IL-8, and a marker of airway remodeling [matrix metalloproteinase (MMP)-9] in EBC in a very small group (n = 4) of children with an asthma exacerbation." (PMID 31106182, 2019). "Higher relative abundance of these bacteria is furthermore associated with an airway immune profile dominated by reduced TNF-α and IL-1β and increased CCL2 and CCL17, which itself is an independent predictor for asthma." (PMID 31676759, 2019). "We first examined the relationship of genotype and asthma at the individual SNP/gene level (TLR4, CD14, TIRAP, and TNFα)." (PMID 30140039, 2018). "Emphasizing the complexity of asthma, markers of TH1 responses, such as TNFα and IFNγ were also elevated in mice of both genotypes." (PMID 29728628, 2018). "In addition to mononuclear phagocytic cells, TNFα may be produced by neutrophils, activated lymphocytes, natural killer cells, endothelial cells, and mast cells; all of them are involved in the pathogenesis of asthma." (PMID 28429138, 2017). "In asthma/A(H1N1)pdm09 mice, IL-6 and TNF-α levels peaked at 3 days post-infection and were higher than those in all other groups." (PMID 28831046, 2017). "It has been previously showed that even within a moderate-to-severe asthma group, a subgroup characterized by elevated TNF-α had higher reports of symptoms and excessive health care use compared to those with lower TNF-α." (PMID 28609485, 2017). "The levels of inflammatory factors (IL-5, IL-6, IL-13, and TNF-α) and those of fibrosis-related proteins (basic fibroblast growth factor (bFGF), IGFBP-3, and TGF-β) were significantly higher in asthma patients than in healthy controls." (PMID 28796252, 2017). "The serum samples of these mice also had lower IL-1β (all P < 0.05), TNF-α (all P < 0.05), IL-4 (all P < 0.05) and IL-5 (all P < 0.05) levels and higher levels of IFN-γ (P < 0.001) compared with the OVA-induced asthma mouse model." (PMID 27134644, 2016). "In fact, there is clear evidence to support the pathobiologic role of TNF-α in COPD, and asthma, mainly in severe refractory asthma." (PMID 27911957, 2016).
asthma (continued). "TNF-α inhibitors (such as infliximab, golimumab and etanercept) are now considered as the potential new medications in COPD and asthma management." (PMID 27911957, 2016). "Vitamin D inhibited three cytokine levels to a comparable degree in fatal asthma- vs. non-asthma-derived ASM, even for IL8, whose TNFα-induced baseline secretion was significantly higher in fatal asthma- vs. non-asthma-derived ASM." (PMID 26207385, 2015). "Elevated levels of TNF have been detected in sputum, bronchoalveolar lavage (BAL), and biopsy samples from patients with asthma." (PMID 26644796, 2015). "Cluster 2 contained an asthma and COPD overlap group, with predominately neutrophilic airway inflammation and elevated levels of IL-1β and TNF-α in addition to being assigned the highest proportion of subjects with bacterial colonization." (PMID 25129678, 2015). "Simultaneously, many studies determined that the de novo synthesis of TNF-α and E-selectin, the critical inflammatory molecules, were mainly regulated by NF-κB activation in ARDS and asthma." (PMID 26343632, 2015). "TNF-α gene is located on chromosome 6p21 within the major histocompatibility complex class III region, which has shown the evidence of linkage to asthma, atopy, and related phenotypes in multiple genome-wide studies." (PMID 24936650, 2014). "Previous work has suggested that pro-inflammatory cytokines including IL1β and TNFα and cyclic strain also induce MMP-1 expression in ASM and are likely to be of relevance to asthma." (PMID 24587395, 2014). "V-D-deficiency intensified ROS release and DNA damage and increased TNF-α, OGG1 and NFκB expression and NFκB phosphorylation in severe asthma exacerbation." (PMID 25380286, 2014). "Main genetic and environmental effect estimates for GSTP1, TNF, and NO2 for asthma and wheeze at school age (pooled data)." (PMID 24465030, 2014). "In the present study, the CRS group with asthma showed severe impairment of NK cell degranulation efficiency and IFN-γ and TNF-α production, whereas these defects were less pronounced in the CRS group without asthma." (PMID 24204766, 2013). "Asthma appeared to modify RV-induced secretion of CXCL10 and TNFα in that RV infection stimulated increased secretion of these cytokines only in subjects without asthma (asthma × RV interaction p values: CXCL10, 0.003; TNFα, 0.0003)." (PMID 24219422, 2013). "TSLP can induce multiple signaling pathways in asthma, including STAT6, IL-4, IL-1β and TNFα, p38 and Jun kinase (JNK )." (PMID 24167583, 2013). "It is of note that dexamethasone, representing the mainstay treatment of severe asthma, inhibited not only dsRNA-induced BSMC generation of proinflammatory cytokines (TNF-α and CXCL8) but also IFN-β and IFN-λ1 in this study." (PMID 23658644, 2013). "TNF-α blockade also ameliorates AHR, impairment of lung function, and quality of life in patients with severe asthma." (PMID 23094102, 2012). "IgE cross-linking also induces the production of IL-6, IL-8, and TNF-α via ERK1/2 and p38 MAP kinases in ASMC isolated from the bronchial tissue of asthma patients, while cytokine production is inhibited by the anti-IgE antibody omalizumab." (PMID 23258953, 2012). "TNF-α is thought to contribute to AHR, airway remodeling and GC resistance in asthma and therefore represents a potential target for therapy." (PMID 23189057, 2012). "Effects of GCE on alveolar macrophages and TNF-α production were evaluated using in vitro MH-S and RAW264.6 cells and in vivo GCE-induced asthma models of BALB/c mice." (PMID 23094102, 2012). "Recent studies indicated that depletion of alveolar macrophages or blockade of TNF-α prevents AHR and progressive inflammatory injuries in an ovalbumin-induced asthma model." (PMID 23094102, 2012). "The synthesis of many inflammatory mediators such as TNFα, IL-4, IL-5, IL-8, RANTES and eotaxins, thought to be important in asthma pathogenesis, are regulated through activation of p38 MAPK." (PMID 18315837, 2008).